ALB (albumin)
Diseases named in the same sentence as ALB in open-access papers (continued):
Sharing a sentence is not in itself a finding about the gene and the disease.
diabetes (continued). "History of coronary artery bypass graft (CABG) or valve surgery, diabetes, ascites, INTERMACS profiles one and two, and low albumin, high blood urea nitrogen (BUN), and high right atrial pressure are associated with high chances of prolonged hospital stay." (PMID 34367750, 2021). "That study included serum creatinine, urinary albumin/creatinine ratio (ACR), age, sex, diabetes duration, follow-up time, HbA1c, and prior cardiovascular disease information to predict final eGFR with an r2 of 0.745 (p < 10−16)." (PMID 34943504, 2021). "In this study, CCVD was correlated with the higher urinary level of MA, age, CRP, lower level of serum albumin, eGFR, ABI, diabetes, cerebral infarction, and CHD." (PMID 34707745, 2021). "Our univariate COX regression analysis revealed that age, BMI, tumor diameter, lymphocyte count, albumin, CA19-9, diabetes, TNM stage, differentiation, and chemotherapy were associated with prognosis of patients." (PMID 34136406, 2021). "Information on age, sex, plasma 25 (OH)D, serum calcium, serum phosphate, parathyroid hormone, dialysis period, hypertension, diabetes, ALT, AST, albumin, alkaline phosphates, and BMI was obtained from the medical records." (PMID 33791129, 2021). "According to these results, serum NLR was positively correlated with age, duration of diabetes, SBP, BUN, CREA, TC, TGs, LDL-c, UA, and WBC and negatively correlated with AST, ALT, and ALB." (PMID 35071771, 2021). "Higher level of urinary MA, age, CRP, D-dimer, lower level of serum albumin, BMI, ABI, eGFR, CLI, diabetes, cerebral infarction, and CHD were related to CCVD in Cox univariate analysis (p<0.05)." (PMID 34707745, 2021). "Higher level of urinary MA, age, CRP, lower level of serum albumin, ABI, diabetes, and CHD were related to MACE, and statin therapy was related to MACE in multivariate analysis (p<0.05)." (PMID 34707745, 2021). "The regression coefficient of diabetes to ACR was 2.4 times higher in comparison to PCR and 5.1 times higher in comparison with non-albumin proteins, in accordance with the concept that high albuminuria is a key marker of diabetic kidney dysfunction." (PMID 33920400, 2021). "The univariate analysis identified that age, diabetes mellitus, PD duration, HGB, lymphocyte, ALB, ALT, CRP, D-D, FIB, folate, VitB12 levels, PNI, NLR, PLR, LMR, and SII were significant factors associated with the ADL score." (PMID 34093411, 2021). "Increased urinary albumin excretion rate (AER) has been shown to predict incident stroke and heart failure in people with diabetes." (PMID 34489262, 2021). "According to our 0-month dataset, the variables diabetes, CHD, age, DBP, LDL-c levels, and serum albumin levels were significantly different between the patients with and without the primary endpoint." (PMID 33988129, 2021). "In our preoperative study model, gender, smoking, diabetes mellitus, HT, COPD, stroke, emergency, age, BMI, blood glucose level, preoperative albumin, troponin, CRP, ejection fraction (EF) and FEV1 values were included and evaluated." (PMID 34236782, 2021). "Age, prevalence of diabetes mellitus (DM), HD vintage, Kt/V urea, PCS, NHALP, albumin, normalized protein catabolic rate (nPCR), phosphate, and iPTH levels differed significantly between two groups." (PMID 34357951, 2021). "There were significant differences in BMI, prevalence of diabetes, prevalence of peptic ulcer disease, prevalence of liver disease, BUN and serum albumin levels among the TC/HDL-C quintiles." (PMID 35011019, 2021). "Higher level of urinary MA, age, CRP, D-dimer, lower level of serum albumin, BMI, ABI, eGFR, CLI, diabetes, and CHD were related to MACE, and statin therapy was related to MACE significantly in Cox univariate analysis (p<0.05)." (PMID 34707745, 2021). "Compared to the patients without mortality, patients with mortality had older age, higher percentage of diabetes, higher SBP and triglyceride, lower albumin, and higher usage of calcium channel blockers." (PMID 33390774, 2021).
diabetes (continued). "Higher level of urinary MA, age, CRP, lower level of serum albumin, ABI, diabetes, and CHD were related to MACE, and higher urinary MA level, age, lower ABI, cerebral infarction, and CHD were related to CVLE." (PMID 34707745, 2021). "Diabetes and normal groups had significantly different male/female ratio, age, K, Cl, Ca, CO2, TBIL, TP, ALB, ALT, Glu, and eGFR (P < 0.05)." (PMID 33505536, 2021). "Despite being nonsignificant, there was a trend towards increased mortality in patient with diabetes, D-dimer levels >1000 ugFEU/L, higher ferritin and prokalsitonin levels, an increased CRP/albumin ratio, and a lower neutrophil/lymphocyte ratio." (PMID 32950045, 2021). "Univariate regression analysis showed that old age, diabetes, high SBP, a low level of albumin, high level of triglycerides, and high usage of calcium channel blockers were associated with increased overall mortality." (PMID 33390774, 2021). "There were also significant increases in the proportion of patients with diabetes who underwent low-density lipoprotein (LDL) cholesterol and albumin: creatinine ratio assessment and had eye examinations in the past year." (PMID 32132750, 2020). "Apart from uric acid indicators, other clinical parameters such as age, ratio of hypertension, ratio of diabetes, HB, CRP, ALB, LDL, HDL, TC, BUN, Scr, Ucr, and Ccr were all significantly different among groups." (PMID 32698778, 2020). "Significant differences based on frailty status were found for age, educational level, overweight, stroke, diabetes, fall history, medications, MMSE scores, GDS scores, serum albumin levels, and all lifestyle activities." (PMID 32987726, 2020). "Participants with high AACS were more likely to be older, with higher BMI and a longer PD duration, more prevalent in hypertension, diabetes, and CVD, with lower serum albumin and HDL, but greater hs-CRP and TG." (PMID 32349690, 2020). "Patient demographics include age, sex, body mass index (BMI), history of diabetes mellitus, and simple routine blood tests, including alanine aminotransferase (ALT), aspartate aminotransferase (AST), platelet counts, fasting glycemia, and albumin." (PMID 32933184, 2020). "PS was calculated based upon variables at the time of SVR; age, male gender, diabetes, ALT, albumin, total bilirubin, platelet count, and liver cirrhosis." (PMID 33217965, 2020). "Univariate analysis identified age (P < 0.001), diabetes (P = 0.015), and CCI (P < 0.001) as variables that were positively related to the MLR, while serum albumin (P = 0.017) was negatively related to the MLR." (PMID 32214908, 2020). "We also performed a subgroup analysis in groups divided according to age, gender, the presence of diabetes, CVD and CKD stages, and albumin and CRP levels." (PMID 33173137, 2020). "Age, prevalence of diabetes, serum AKP, albumin, and iPTH were significantly higher in patients with HD compared to PD patients (p < 0.05)." (PMID 32216514, 2020). "Indicators of diabetes metabolic control: mean glycemia, glycated hemoglobin (HbA1c), total cholesterol and triglycerides, creatinine, glomerular filtration rate (GFR), albumin–creatinine ratio in urine." (PMID 32295214, 2020). "Univariate analysis identified that the following factors were significantly associated with the OS for patients with BCLC B-stage disease: diabetes; PT; APTT; serum levels of AST, ALT, ALB, TB, and AFP; and BMI." (PMID 32280472, 2020). "The independent factors affecting HCC occurrence identified by multivariate analysis were the serum albumin (ALB) level before SVR for NC patients and the ALBI score, platelet count, and diabetes before SVR for LC patients." (PMID 33284844, 2020). "Correlation of ECW/BCM or LTI to the risk of death were analyzed in the subgroups based on sex, BMI, MAP, diabetes, chronic heart failure, infection, CCI, incident dialysis, hemodialysis vintage, vascular access, serum albumin, hemoglobin and iPTH." (PMID 32576950, 2020).
diabetes (continued). "The levels of urinary albumin and liver-type fatty acid binding protein (L-FABP) excretion in diabetes + STD rats were markedly increased compared to those of the control rats at the end of the study." (PMID 32145700, 2020). "At baseline, older age, the presence of diabetes, gender, low concentrations of ALT, albumin, bilirubin and haemoglobin and high concentrations of ALP, high UACR, systolic blood pressure, WHR and HbA1c were significantly associated with lower eGFR categories." (PMID 33261565, 2020). "Only the CV and diabetes groups had higher mean blood urea nitrogen (BUN) values, lower serum creatine, and lower plasma albumin as expected given the worse renal conditions." (PMID 33511378, 2020). "We demonstrated that NEAT1 was significantly upregulated in both bovine serum albumin (BSA)-stimulated HK2 cells and mice with HFD- and STZ-induced diabetes." (PMID 32054986, 2020). "The NAFLD fibrosis score (NFS) is based on age, BMI, impaired fasting glycemia or diabetes mellitus, AST/ALT ratio, platelet count, and the serum level of albumin." (PMID 32933184, 2020). "The administration of somatostatin analogs to patients with type 1 diabetes mellitus has also been reported to reduce serum IGF-1 and urinary albumin." (PMID 31540583, 2019). "The AIC, which represents the goodness of fit of the CPM, was worse for model 2 (the simpler model, comprised of age, sex, and eGFR) than for model 7 (including model 2 plus SBP, diabetes, log-UACR, serum albumin, and Hb)." (PMID 30069609, 2019). "Inflammation contributes to the pathogenesis of diabetes, in which SAA and other inflammatory markers, including CRP, TNF, and MCP-1, increase in parallel with urinary albumin." (PMID 30899260, 2019). "The risk of CKD or ESRD increased with the severity of AKI, advanced age, diabetes mellitus, hypertension, heart failure, increased CCI during AKI episodes, and low serum albumin levels." (PMID 30703146, 2019). "The combination of Tregitope-albumin fusions and PPI peptides reduced the incidence of severe diabetes and reversed mild diabetes, over 49 days of treatment and observation." (PMID 31695065, 2019). "Covariates selected for model of ICU admission included SBP, blood urea nitrogen, P, ferritin, diabetes, CAD, ALB, CRP." (PMID 30759782, 2019). "The additional inclusion of SBP, diabetes, log-UACR, serum albumin, and Hb (model 7) resulted in substantially different probabilities, with the predicted probability of ESKF onset at 3 years reduced by 7.6% in patient A and increased by 11.9% in patient B." (PMID 30069609, 2019). "Model 2, with age, sex, and eGFR, had a larger AIC (2,350.1) compared to that for model 7 (model 1 plus SBP, diabetes, log-UACR, serum albumin, and Hb) and model 9 (model 7 plus log-iPTH and log-FGF-23), which had AICs of 2,216.3 and 2,211.6, respectively." (PMID 30069609, 2019). "For the PCV, albumin globulin ratio, and HDL-cholesterol test indexes, almost half or more than half of the patients with diabetes had low test results." (PMID 29587624, 2018). "Next, we performed multiple regression analysis adjusted for age, duration of diabetes, SBP, BMI, HbA1c, fasting C-peptide, LDL-C, HDL-C, and urine albumin." (PMID 30571795, 2018). "HTx patients had lower lymphocyte, platelets, glucose, total proteins and albumin at T1; differences with LVAD patients vanished during rehabilitation when new cases of diabetes were observed in HTx." (PMID 30018333, 2018). "As an inner layer of glomerular filtration barrier, GECs impairment has been proved to be correlated with the urinary albumin creatinine ratio, which happened before podocytes and GBM damage in rodent and human diabetes." (PMID 30319431, 2018). "In patients with diabetes, MFR decreased progressively in relation to albumin urinary excretion (normoalbuminuria: 2.9 ± 1.1, microalbuminuria: 2.3 ± 1.0, macroalbuminuria: 1.8 ± 0.7; p < 0.0001)." (PMID 29325551, 2018).
diabetes (continued). "Patients with CAN progression were older; had a longer duration of diabetes; used more insulin; and had a higher level of HbA1c, fasting plasma glucose, LDL-cholesterol, and urinary albumin excretion." (PMID 30071872, 2018). "These included age, comorbid conditions like diabetes and hypertension, admission creatinine, peak creatinine, pH, O2, CO2, HCO3, albumin, presence of oliguria, need for vasopressor, stay in ICU, and severity of AKI." (PMID 29853800, 2018). "We identified 58,182 patients diagnosed with diabetes from 2000–2008 and examined the level of performance for seven QoC measurements (HbA1c, LDL, albumin-creatinine-ratio, fundus/foot examinations, BMI and Blood-pressure) at diagnosis year." (PMID 30540832, 2018). "Based on univariate analysis, age, albumin, uric acid, sclerostin, CIMT, diabetes and history of cardiovascular disease (p < 0.05) were included." (PMID 30314461, 2018). "Compared with NC, the levels of ALB, PA and TRF were significantly lower in diabetes groups (MC, WP and SCCOPs-treated groups) on days 4, 7 and 14 (p < 0.05)." (PMID 29316680, 2018). "Urine albumin, albumin/creatinine ratio, NGAL/creatinine ratio, and IgG significantly correlated with known duration of diabetes." (PMID 30158836, 2018). "The duration of diabetes, HCY, CYSC, laminin urinary albumin excretion rate (LnUAER), eGFR, and the prevalence of eGFR <90 mL/min and eGFR <60 mL/min were significantly lower in quartile 1 of serum OIF compared with the other quartiles." (PMID 30075597, 2018). "Second, urinary albumin was used to define CKD, which has already been recognized as an important predictor of kidney function decline especially, in diabetes patients." (PMID 28592280, 2017). "After backwards elimination, predictors of SCD in AF using the Fine-Gray method included higher age, increased BMI, CHD, hypertension, diabetes, current smoker, LVH, and decreased albumin." (PMID 29117224, 2017). "In researches on patients with both Insulin Dependent Diabetes Mellitus (IDDM) and Non-Insulin Dependent Diabetes Mellitus (NIDDM), urinary secretion of albumin has been discovered to be predictor of improvement in proteinuria and end-stage DN." (PMID 28589103, 2017). "Pathological urinary albumin excretion (UAE) is one of the most robust and earliest signs of diabetes-induced kidney injury." (PMID 28570649, 2017). "Clinically, several enzymes and substance levels are used as biochemical markers for early diagnosis of diabetes and its complications, including AST, ALT, BUN, CRE and ALB." (PMID 28233836, 2017). "Variables entered in the propensity model included age, gender, platelet counts, leukocyte counts, hemoglobin levels, serum albumin and ALT levels, HbA1c, histories of diabetes mellitus and alcohol intake, hypertension, and hyperlipidemia." (PMID 28797106, 2017). "To investigate associations of PEWSGA with age, gender, co-morbidities (CVD diabetes), renal replacement therapy (RRT), anthropometry (%HGS, LBMI, FBMI BMI), serum albumin, and inflammatory status, we divided the patients according to these factors." (PMID 29211778, 2017). "Our model includes not only age and diabetes mellitus status derived from the FRS, but also history of CV events, dialysis time per session and phosphate and albumin levels as new factors." (PMID 28273175, 2017). "Patients with a serum albumin level >3.0 g/dL (P < 0.01), cancer antigen 19‐9 ≤200 U/mL (P = 0.03), carcinoembryonic antigen ≤10 ìg/L (P < 0.01) or patients without a history of cirrhosis (P < 0.01) or diabetes (P = 0.02) were associated with a greater length of overall survival." (PMID 27389416, 2017). "In normoalbuminuric diabetics, the excretion rate of RBP was significantly higher compared to control subjects and correlated to the excretion rate of NAG and albumin." (PMID 27293888, 2016).
diabetes (continued). "Compared with group 3 and group 2 patients, group 1 patients were older; had a higher incidence of diabetes mellitus (DM); had lower BMI and nPCR; and had lower serum levels of albumin, hemoglobin, calcium-phosphorus (CaxP) product, BUN, creatinine, cholesterol, triglycerides, and TIBC." (PMID 27780214, 2016). "While earlier studies focused on the relationships between urinary albumin excretion and diabetic optic neuropathy or ocular hypertension, we focused on the influence of albuminuria on OAG by excluding patients with diabetes and impaired glucose tolerance." (PMID 28006020, 2016). "This retrospective review evaluated ciNPT over the post-sternotomy incisions of 27 cardiac patients with multiple comorbidities, including obesity, diabetes, COPD, low albumin, and hypertension." (PMID 27026831, 2016). "Present finding indicates that diabetes can induce nephropathy through the increase BUN, plasma Cr level and decrease in plasma albumin levels." (PMID 27921024, 2016). "Glycated albumin regulates VEGF expression to promote proteinuria and glomerulosclerosis in diabetes, suppresses insulin secretion in pancreatic β-cells, and stimulates cultured retinal microglia to secrete inflammatory cytokines." (PMID 27034961, 2016). "Together, smoking, LDL-C, BMI, HDL-C, and diabetes mellitus accounted for 76.01% of PAR for first incident AMI, increasing substantially with addition of albumin, Lp (a), or both." (PMID 27748452, 2016). "As expected, CKD 5 patients had a higher burden of comorbidities, including diabetes mellitus, CVD and PEW, lower mGFR, plasma albumin and hemoglobin levels and higher levels of creatinine, hsCRP and IL-6, compared with CKD 3–4 patients and controls." (PMID 26751065, 2016). "Baseline urine albumin/creatinine ratio (ACR) of 762 newly diagnosed, drug-naïve patients with type 2 diabetes mellitus was measured." (PMID 27057866, 2016). "Variables found to be statistically significant in univariate analyses were entered into multivariate lineal regression model, age, diabetes, current smoking status, AVD history, albumin,phosphorus, iPTH and NLR." (PMID 27881094, 2016). "Of these, NFS is the most commonly used, composed of six variables including age, BMI, diabetes, AST/ALT ratio, platelet count, and serum albumin." (PMID 27284700, 2016). "However, in Model 2, adjusted for the same variables than Model 1 plus diabetes and SBP, urinary RBP remained positively associated to albuminuria, serum phosphorus, HDL-cholesterol and PWV, and inversely associated to CKD-EPI eGFR, bicarbonate, serum albumin and left atrium diameter." (PMID 27655369, 2016). "Age, sex, history of diabetes mellitus or hypertension, use of ACE inhibitors or ARBs, hemoglobin level, and albumin level showed significant differences across the eGFR groups." (PMID 27149474, 2016). "Combining the direct markers with simple markers such as age, BMI, presence of diabetes, AST/ALT-ratio, albumin, and platelet count improved AUROC to 0.98." (PMID 27936091, 2016). "We adjusted for confounding by gender, age, cirrhosis etiology, diabetes, history of HE, Model for Endstage Liver Disease (MELD) score, serum sodium, albumin, lactulose use, rifaximin use, and benzodiazepine/barbiturate sedation." (PMID 27457247, 2016). "In conclusion, urinary PDGF‐C levels were elevated in diabetic mice in a similar fashion to that of albumin, an established early marker of diabetic kidney damage, indicating the possible adoption of urinary PDGF‐C as a prediction of kidney injury in diabetes." (PMID 27033449, 2016). "The TG/HDL-C ratio was an independent determinant of FMD (β = −0.25 p = 0.02) along with TG, HDL-C, hsCRP, serum albumin, phosphate levels, systolic blood pressure, PTH, eGFR and the presence of diabetes mellitus." (PMID 25885289, 2015).